FOXC2 (forkhead box C2)
Diseases named in the same sentence as FOXC2 in open-access papers (continued):
Sharing a sentence is not in itself a finding about the gene and the disease.
metastatic tumors (3 papers, 2018 to 2025). "Additionally, among patients with metastatic tumors that have amplified wild type AR, increased FOXC2 mRNA in tumors correlated with significantly reduced median overall survival." (PMID 31379747, 2019). "Human-specific gene expression of SNAI1, GSC, FOXC2, KRT19, and STAM2, presumably originating from DTCs, was detected in the BM of all xenograft mice that also developed metastatic tumors." (PMID 29291741, 2018).
oral squamous cell carcinoma (3 papers, 2014 to 2021). "For example, Forkhead box protein C2 (Foxc2) is a known regulator of angiogenesis in both wound healing and oral squamous cell carcinoma." (PMID 32082384, 2019). "In the present study, we examined the expression of Prox1 and FOXC2 proteins in specimens from 163 cases with oral squamous cell carcinoma (OSCC)." (PMID 24647631, 2014). "FOXC2 is also an important regulator of epithelial to mesenchymal transition (EMT) in cancer cells, while the role of FOXC2 in oral squamous cell carcinoma (OSCC) remains unknown." (PMID 24647631, 2014).
osteoporosis (3 papers, 2022 to 2023). A condition of reduced bone mass, with decreased cortical thickness and a decrease in the number and size of the trabeculae of cancellous bone (but normal chemical composition), resulting in increased fracture incidence. "Together with the activation of Foxc2, the suppression of Osterix leads to switching the cell fate and functional capacity in osteoblast-lineage cells, contributing to osteoporosis." (PMID 37508475, 2023). "The study also showed that glucocorticoids suppress Osterix expression but activate Foxc2 in osteoblast lineage cells to switch the cell fate and functional capacity, contributing to osteoporosis." (PMID 37887278, 2023). "In humans, variants in FOXL1 and FOXC2 are associated with a reduced bone mineral density (BMD) and a risk of osteoporosis." (PMID 35885890, 2022).
type 2 diabetes (3 papers, 2011 to 2025). "Our study aims to investigate differences in the gut microbiota of type 2 diabetes patients with distinct FOXC2 gene C512T polymorphisms." (PMID 41404514, 2025). "To further investigate species-specific differences in the gut microbiota associated with the FOXC2 gene C-512T polymorphism in patients with type 2 diabetes, we employed LefSe analysis for the final assessment." (PMID 41404514, 2025). "We will continue to explore the specific mechanisms by which Collinsella influences the pathogenesis of type 2 diabetes through the FOXC2 gene." (PMID 41404514, 2025). "In this study, the expression of FOXC2 and selected genes involved in mitochondrial function and biogenesis in healthy subjects and in a matched cohort with type 2 diabetes patients before and after treatment with rosiglitazone was determined." (PMID 22098677, 2011). "Collinsella, as a potential key pathogen in type 2 diabetes, may be involved in the metabolic processes of the FOXC2 gene in patients with type 2 diabetes." (PMID 41404514, 2025).
breast tumor (2 papers, 2014 to 2018). "We also found upregulation of FOXC2 by ERβ2 and ERβ5; expression of FOXC2 is associated with claudin-low/basal B breast tumors or other EMT-/CSC-enriched tumors." (PMID 29552303, 2018). "With exception of SNAI3, all the up-regulated genes are known to be involved in breast tumor malignancy and include the transcription factor FOXC2, PDGFRB and members of the WNT family, whose products are known to sustain the metastatic process of breast tumors." (PMID 24962430, 2014).
Cirrhosis (2 papers, 2018 to 2023). A chronic disorder of the liver in which liver tissue becomes scarred and is partially replaced by regenerative nodules and fibrotic tissue resulting in loss of liver function. "High expression of FOXC2 in HCC was significantly associated with the progression of cirrhosis in the background liver." (PMID 29801468, 2018). "We found that matrix stiffness induces HSCs activation into myofibroblasts and enhanced nuclear accumulation of FOXC2, moreover, FOXC2 was highly expressed in fibrosis or cirrhosis tissues." (PMID 37705741, 2023).
cystic hygroma (2 papers, 2012 to 2016). A benign lymphatic neoplasm usually arising from the neck and characterized by cystic dilation of the lymphatic vessels. "We report the prenatal diagnosis of cystic hygroma that was subsequently identified to have haploinsufficiency of the FOXF1 and FOXC2 genes via array comparative genomic hybridization (aCGH)." (PMID 23074687, 2012). "There has been one prenatal case reported in the literature with septated cystic hygroma, fetal hydrops, and a single umbilical artery presented at the 18th weeks of gestation, in which aCGH identified a deletion of 1,1 Mb in size, including both FOXF1 and FOXC2." (PMID 27846804, 2016).
endometriosis (2 papers, 2024 to 2025). The growth of functional endometrial tissue in anatomic sites outside the uterine body. "In summary, EMT-related transcription factors such as Snail, Slug, Twist, ZEB1, and FOXC2 are central to the regulation of epithelial plasticity and invasive behavior in endometriosis." (PMID 40806587, 2025). "Cancers that have stemness properties are resistant to chemotherapy, and this may also apply in the case of endometriosis; FOXC2 (forkhead box protein C2) and PGF (platelet growth factor) are involved in the process." (PMID 39684461, 2024).
Intellectual disability (2 papers, 2022 to 2023). "A number of transcription factors, including FOXC2 and GATA1, play a role in neuronal dysfunction and intellectual disability, which are affected by impaired protein synthesis and splicing." (PMID 37359008, 2023). "Impairments in protein synthesis and splicing mediated in part by transcription factors such as FOXC2, GATA1, contribute to impaired neuronal function and concurrence of intellectual disability and craniofacial anomalies in our patients." (PMID 35436926, 2022).
ischemia (2 papers, 2021 to 2025). A hypoperfusion of the BLOOD through an organ or tissue caused by a PATHOLOGIC CONSTRICTION or obstruction of its BLOOD VESSELS, or an absence of BLOOD CIRCULATION. "In murine models of injury-induced ischemia, tissue nanotransfection rescued ischemic tissue by delivering reprogramming factors EFF [E-26 transformation-specific variant 2 (Etv2), friend leukemia integration 1 (Fli1) and forkhead box C2 (Foxc2)] directly into skin cells." (PMID 40606909, 2025).
lymph node metastases (2 papers, 2015 to 2022). "High expression of FOXC2 is associated with lymph node metastases (OR = 3.33, 95% CI: 2.65–4.19), TNM stage (OR = 3.09, 95% CI: 2.00–4.78), and age (OR = 1.26, 95% CI: 1.06–1.50), according to the pooled ORs." (PMID 36425886, 2022). "Increased expression of FOXC2 is associated with unfavored OS, lymph node metastases, TNM stage, and age." (PMID 36425886, 2022). "In this analysis, increased expression level of FOXC2 is associated with poor prognosis, as well as TNM stage, lymph node metastases, and age." (PMID 36425886, 2022). "FOXC2 belongs to the forkhead family of transcription factors, and this gene is significantly related to the degree of lymph node metastasis in CRC42 and might correlate with disease survival time." (PMID 26239918, 2015). "Additionally, increased FOXC2 was closely associated with age, TNM stage and lymph node metastasis, suggesting that FOXC2 could be a useful biomarker for predicting prognosis in human solid tumors based on clinical pathology." (PMID 36425886, 2022).
squamous cell carcinoma (2 papers, 2016 to 2020). A carcinoma arising from squamous epithelial cells. "Finally, we explored the correlation of ZNF750 with FOXC2 expression level across various human squamous cell carcinomas." (PMID 32341351, 2020). "Additionally, we also conducted the correlation analysis of ZNF750 with FOXC2 transcriptional level in ESCC and other squamous cell carcinomas based on the TCGA database." (PMID 32341351, 2020). "High expression of FoxC2 showed a significant correlation with poorer outcome in patients with adenocarcinoma (p = 0.018), whereas no prognostic impact was verified in those with squamous cell carcinoma." (PMID 26758745, 2016).
anterior synechia (1 paper, 2024). "In addition, anterior synechia was observed in eyes with mutations in PITX2, FOXC1, and FOXC2, which are required for anterior segment development and angiogenic privilege." (PMID 38263030, 2024).
arteriovenous malformations (1 paper, 2018). "Furthermore, knock-down of FOXC2 in combination with Etv2 has been shown to disrupt vascular development in the zebrafish and mouse embryo compound mutants for FOXC1 and FOXC2 display arteriovenous malformations." (PMID 29963552, 2018).
astrocytoma (1 paper, 2022). "Except for CCND2, FLT1, FOXC2, KDR, KRT14, and TEK, the mRNA expression ratio of cancer pathway-associated genes in the astrocytoma grade III cell line (SW1088) was comparable to that of other tumour cell lines." (PMID 36142793, 2022).
benign prostatic hyperplasia (1 paper, 2019). A non-cancerous nodular enlargement of the prostate gland. "FOXC2 was strongly expressed in primary carcinomas, including castration resistant tumours and metastatic lesions as compared to benign prostatic hyperplasia." (PMID 31464093, 2019).
bone metabolism disorders (1 paper, 2023). "Functional state changes of CREM, FOSL2, FOXC2, RUNX2, and CREB3L1 regulons regarding immunity, cell proliferation, and differentiation identified the important cell stages or subtypes that may be predominantly affected by bone metabolism disorders." (PMID 36793138, 2023).
Chylothorax (1 paper, 2020). The presence of chyle in the thoracic cavity. "At P6, a majority of compound EC-Foxc1; Foxc2 mutant mice (48/78, 61.5%) developed severe chylous ascites and chylothorax (data not shown)." (PMID 32510325, 2020).
cleft palate (1 paper, 2010). Cleft palate is a fissure type embryopathy that affects the soft and hard palate to varying degrees. "Similarly, FOXF1 and Foxf1, but not FOXC2 or Foxc2, are clearly associated with abnormalities of intrinsic pulmonary vasculature and lung lobation while inactivation of FOXC2 and Foxc2, but not FOXF1 or Foxf1, is associated with cleft palate." (PMID 19822228, 2010).
congenital glaucoma (1 paper, 2019). "FOXC2, PITX2 and CYP1B1 variants identified in congenital glaucoma patients." (PMID 30657791, 2019).
coronary artery disease (1 paper, 2024). "Thus, the upregulation of FOXC2, which is involved in developing and functioning endothelial progenitor cells that contribute to vascular regeneration in coronary artery disease, might have promoted vascular regeneration in the DCD allograft of the HTK-N group." (PMID 38396938, 2024).
Cyanosis (1 paper, 2014). Bluish discoloration of the skin and mucosa due to poor circulation or inadequate oxygenation of arterial or capillary blood. "Lastly, we addressed the question of whether cardiovascular abnormalities could be the primary cause of respiratory distress and cyanosis in KLEIP−/− mice as has been described for Foxc2- and Sema3c-deficient single-mutant mice." (PMID 24785085, 2014).
cyst (1 paper, 2013). A sac-like closed membranous structure that may be empty or contain fluid or amorphous material. "All SEDAC subjects without FOXC2 mutations had a single cyst, which occurred in the thoracolumbar junction, whereas 7 of 10 SEDAC subjects with FOXC2 mutations had multiple cysts that occurred in various areas, ranging from the upper thoracic to the sacral regions." (PMID 24278289, 2013). "Furthermore, there were differences in the cyst numbers; all SEDAC subjects without FOXC2 mutations had a single cyst, while SEDAC subjects with FOXC2 mutations frequently had multiple cysts." (PMID 24278289, 2013).
dilated cardiomyopathy (1 paper, 2024). Cardiomyopathy which is characterized by dilation and contractile dysfunction of the left and right ventricles. "Further, to verify the correlation between telomere length and FOXC1/FOXC2, we performed TelC Q-FISH and immunohistochemistry staining on patient heart tissue chips consist of DCM (dilated cardiomyopathy), ICM (ischemic cardiomyopathy) and CHD (coronary atherosclerotic heart disease) biopsies." (PMID 38634789, 2024).
disc degeneration (1 paper, 2016). "We demonstrated that FoxC2 was frequently upregulated in human degenerative NP tissue and significantly associated with disc degeneration grade." (PMID 26824865, 2016). "In degenerative NP tissue, FoxC2 was markedly upregulated and positively correlated with increased disc degeneration." (PMID 26824865, 2016). "However, expression of FOXC2 was positively correlated with the disc degeneration grade (n = 36, r = 0.881, p<0.05)." (PMID 26824865, 2016). "The mRNA expression level of FoxC2 was positively correlated with disc degeneration grade." (PMID 26824865, 2016).
Esophageal atresia (1 paper, 2009). A developmental defect resulting in complete obliteration of the lumen of the esophagus such that the esophagus ends in a blind pouch rather than connecting to the stomach. "The lack of intestinal atresia in group 3 suggests that either FOXC2 or FOXL1 may also contribute to this phenotype in humans, despite the fact that, in mice, haploinsufficiency for Foxf1 alone is associated with esophageal atresia." (PMID 19500772, 2009).
fibrosis (1 paper, 2023). the formation of excess fibrous connective tissue in an organ or tissue in a reparative or reactive process. "To investigate whether targeting FOXC2 could repress further progression of established liver fibrosis in vivo, we utilized AAV6 carrying shRNA targeting FOXC2 to intervene CCl4 or BDL-induced mice fibrosis model." (PMID 37705741, 2023).
gastric adenocarcinoma (1 paper, 2017). "We show that up-regulation of FOXC2 and FOXQ1 are likely to be involvedin the progression of gastric adenocarcinoma." (PMID 28580309, 2017).
gastric tumors (1 paper, 2017). "This is consistentwith results herein showing that FOXC2 hasalso significantly higher transcript levels in highgrade gastric tumors." (PMID 28580309, 2017).
glomerulosclerosis (1 paper, 2018). A hardening of the kidney glomerulus caused by scarring of the blood vessels. "Our study also demonstrated that loss of Wt1 in mature podocytes is associated with a reduction of FoxC2 expression and upregulation of Notch pathway components coincident with onset of glomerulosclerosis and albuminuria." (PMID 29398135, 2018).
Granulosa cell tumour (1 paper, 2023).
histiocytic sarcoma (1 paper, 2016). An aggressive malignant neoplasm with a poor response to therapy, usually presenting as stage III/IV disease. "Interestingly, all of these genes, with the exception of Foxc2, have been previously associated with various types of sarcoma in either human or rodent studies and increased CCL2 gene expression has been directly correlated with histiocytic sarcoma in canine patients." (PMID 27105514, 2016).
hyperhomocysteinemia (1 paper, 2014). A serious metabolic condition caused by mutations in the MTHFR gene, medications, or nutritional deficiency. "Recent areas of study have focused on connexins, alterations in thrombomodulin, matrix Gla protein (MGP), Forkhead box protein C2 (FOXC2), hyperhomocysteinemia, and Type-I plasminogen activator inhibitor polymorphisms." (PMID 25520775, 2014).
Hyperinsulinemia (1 paper, 2021). An increased concentration of insulin in the blood. "Under such conditions, hyperinsulinemia, a common side effect of ADT, enhances PCa cell plasticity, thus increasing tumor migration and invasiveness, by upregulating the Forkhead Box Protein C2 (FOXC2) transcription factor." (PMID 33692752, 2021).
idiopathic scoliosis (1 paper, 2016). A scoliosis with no known cause. "FOXC2 expression in the degenerative NP tissue was significantly higher compared to the idiopathic scoliosis NP tissue as determined by real-time PCR." (PMID 26824865, 2016).
intervertebral disc degeneration (1 paper, 2016). "Combination therapy using BMP-7 and FoxC2 may be beneficial to the treatment of intervertebral disc degeneration." (PMID 26824865, 2016).
kidney cancer (1 paper, 2016). Primary or metastatic malignant neoplasm involving the kidney. "Therefore, overexpression of FOXC2 was considered to be associated with kidney cancer metastasis and was chosen for further gene knockdown studies." (PMID 27283491, 2016). "qRT-PCR was performed on all six cell lines for the three candidate genes (RELN, FOXC2, and CLIP4) to identify those with significant fold-changes in gene expression in the kidney cancer cell lines compared to the normal kidney cell line." (PMID 27283491, 2016).
liver cirrhosis (1 paper, 2018). "In the present study, we demonstrated that a high expression of the EMT inducer, FOXC2, in primary HCC samples is associated with liver cirrhosis, malignant potential, high serum AFP, and poor prognosis." (PMID 29801468, 2018). "High FOXC2 expression was correlated with liver cirrhosis (P = 0.0296), poor differentiation (P = 0.0302), high serum AFP levels (P = 0.00078), and the Ki-67 labeling index (P = 0.0348)." (PMID 29801468, 2018). "A high expression of FOXC2 was observed in 26 of 84 cases, and expression was significantly correlated with background liver cirrhosis, poor tumor differentiation, high serum AFP, and elevated cell proliferation markers." (PMID 29801468, 2018).
liver disease (1 paper, 2025). "In addition, state #5 was identified as PDPN, FOXC2, and PROX2-expressing lymphatic-specific ECs; state #6 as a subpopulation expressing PLAT, whose protein level is increased in patients with liver disease; and, states #23, #32 and #34 as liver-specific liver sinusoidal ECs (LSECs)." (PMID 39748128, 2025).
male infertility (1 paper, 2023). The inability of the male to effect fertilization of an ovum after a specified period of unprotected intercourse. "Germ cell-specific Foxc2 knockout resulted in an accelerated exhaustion of SSCs and eventually led to male infertility." (PMID 37610429, 2023).
myeloma (1 paper, 2019). "Notably, hypoxia has been shown to promote myeloma cell dissemination from the bone marrow to the peripheral blood through the downregulation of E-cadherin and the upregulation of the epithelial to mesenchymal transition proteins SNAIL, FOXC2, and TGFβ1." (PMID 31020046, 2019).
oral cancer (1 paper, 2021). "Some proangiogenic factors have been reported in the development of lymphangiogenesis in oral cancer, such as prospero homeobox 1, forkhead box C2, and astrocyte elevated gene-1." (PMID 33668218, 2021).
ovarian tumors (1 paper, 2022). "In a recent immunohistochemistry analysis of ovarian tumors, FOXC2 expression was detected in more than 50% of HGSOC." (PMID 36230774, 2022).
pancreatic adenocarcinoma (1 paper, 2019). "Moreover, the online database (ChIPbase) demonstrated an obvious correlation between HIF-1α and FOXC2 mRNA expression in pancreatic adenocarcinoma (PDDA)." (PMID 31367258, 2019).
Peritoneal Fibrosis (1 paper, 2025). Disorder characterized by a wide range of structural changes in PERITONEUM, resulting from fibrogenic or inflammatory processes. "Notably, AE ameliorates FOXC2‐driven peritoneal fibrosis by impeding NETs formation and EMT changes through the TGF‐β1‐Smad2/3 pathway." (PMID 41082405, 2025).